WIF1 (Wnt inhibitory factor 1)
Diseases named in the same sentence as WIF1 in open-access papers (continued):
Sharing a sentence is not in itself a finding about the gene and the disease.
colon cancer (16 papers, 2012 to 2025). "Previous reports indicate that wif-1 is reduced or deleted in a variety of tumor cells, including colon cancer, endometrial cancer and chondrosarcoma." (PMID 32795328, 2020). "In this work, WIF-1 gene, as an anti-oncogene, was delivered into colon cancers with the help of the FA-PEA polymer." (PMID 26883682, 2016). "Additionally, genistein can revive Wif1 expression in HT29 colon cancer cell lines by modifying Wif1 methylation." (PMID 40969409, 2025). "In addition, propofol attenuates metastasis of colon cancer by STAT3/HOTAIR axis through the activation of WIF-1 and the suppression of Wnt signaling." (PMID 34789263, 2021). "We revealed that propofol could suppress the development and metastasis of colon cancer by blocking the interaction of STAT3 with HOTAIR promoter and downregulating the expression of HOTAIR, which causes the repression of Wnt signaling pathway via WIF‐1." (PMID 31953926, 2020). "Taken together, our results revealed that propofol could promote apoptosis and inhibit invasion, mainly through its inhibition on STAT3 and HOTAIR to deactivate Wnt signaling pathway by increasing WIF‐1 expression levels, which might serve as a therapeutic role for colon cancer." (PMID 31953926, 2020). "- Overexpression of miR-766 contribute to inhibition of colon cancer development by decreasing methylation of tumor suppressor genes including DKK2, WIF1, SFRP1, and SFRP2." (PMID 37205191, 2023). "Dietary administration of black raspberries resulted in demethylation of WIF1, SOX17, and GKI in in vivo colon cancer models." (PMID 33375383, 2020). "In studies of other authors, dietary application of black raspberries (BRB) rich in numerous flavonoids such as anthocyanidins led to demethylation of tumor-suppressor gene promoters, including WIF1, SOX17, and GKI in precancerous colon cancer in vivo." (PMID 32204409, 2020). "Little is known about EBV-miRNAs in colon cancer, however, miR-BART19-3p is shown to target WIF1, a gene important in colon cancer, and miR-BART1 is shown to target PSAT1, a gene shown to promote proliferation of tumor cells." (PMID 30786859, 2019). "The apoptosis of colon cancer cells in vitro induced by the treatments of PEA/WIF-1 and FA-PEA/WIF-1 complexes was qualitatively detected by Hoechst 33258/PI and DAPI respectively." (PMID 26883682, 2016). "Combined treatment of 5-aza-dC with the histone deacetylase inhibitor trichostatin A restores WIF-1 expression, and restoration of WIF-1 inhibits colony formation, cellular proliferation, and anchorage-independent growth of TE-1 ESCC cells or SW48 colon cancer cells." (PMID 34488905, 2021). "MiR-590-3p promoted colon cancer progression via WIF1 and DKK1, and it might be a promising biomarker for colon cancer treatment." (PMID 33439933, 2021). "Furthermore, qRT-PCR analysis for Wnt target genes (including cMyc, Ascl2, Axin2, CD44, CD1, Sox17, Wif1 and Tiam1) did not identify any significant differences between the colonic tumours isolated from both cohorts of mice." (PMID 25881306, 2015).
glioblastoma (16 papers, 2013 to 2024). The most malignant astrocytic tumor (WHO grade IV). "Down-regulation of WIF1 expression induced by miR-552 can cause glioblastoma to significantly reduce the number of cells in the S phase and increase the number of cells in the G1 phase, thereby inhibiting cell growth and differentiation." (PMID 33033505, 2020). "For example, MALAT-1 induces EMT in various cancers via the Wnt/β-catenin signalling pathway, while loss of WIF1 enhances the migratory potential of glioblastoma cells through WNT5A activation mediated by MALAT1." (PMID 29701689, 2018). "For example, HOTAIR (HOX transcript antisense RNA) epigenetically silences the Wnt inhibitor WIF1, while the loss of WIF1 enhances the migratory ability of glioblastoma cells through WNT5A activation mediated via MALAT1." (PMID 29416704, 2018). "WIF1 reduced glioblastoma migration in vivo and in vitro by inhibiting the Wnt5a/p38-MAPK/Ca2+ pathway." (PMID 39687904, 2024). "Meanwhile, down-regulation of WIF1 has been shown to enhance the migratory aptitude of glioblastoma via WNT5A that induces expression of MALAT1." (PMID 34178658, 2021). "WIF1 downregulation has been reported to enhance the migration of glioblastoma cells and to simulate the sensitivity of glioblastomas for Wnt signaling inhibitors." (PMID 32604718, 2020). "Re-expression of WIF1 in glioblastoma inhibits migration, suggesting a role of WIF1 in the regulation of cell cycle and proliferation." (PMID 27716781, 2016). "WIF1 acting as a Wnt antagonist and tumor suppressor is involved in the pathogenesis of some brain cancers, such as astrocytomas, glioblastoma and neuroblastoma." (PMID 27716781, 2016). "Other researchers have reported that endogenous oligodendrocytes are capable of repressing the growth and proliferation of glioblastoma cells by paracrine signaling via WNT inhibitory factor 1, and this explanation strongly supports the seemingly paradoxical result in our study." (PMID 36233730, 2022). "In glioblastomas, WIF1 silencing is mediated by genomic deletion, promoter methylation, or both." (PMID 24289328, 2013). "MiR-552 inhibits the expression of WIF1 and may promote the cell cycle of glioblastoma cells." (PMID 33033505, 2020). "Wnt inhibitory factor 1 (WIF1) attenuates non-canonical Wnt signaling through downregulation of MALAT1, thereby suppressing migration, but not proliferation, of glioblastoma cells." (PMID 33980320, 2021).
cervical carcinoma (13 papers, 2013 to 2026). A carcinoma arising from either the exocervical squamous epithelium or the endocervical glandular epithelium. "Consistent with our in vitro results, WIF1 gene transfer induced significant apoptosis in cervical cancer cells in vitro." (PMID 38339068, 2024). "The remaining genes (DAPK1, RARB, SLIT2 and WIF1) were evaluated for their ability to identify cervical cancer cases in relation to HPV infection and age." (PMID 25826459, 2015). "Genes encoding several key regulators of the oncogenic Wnt/β-catenin pathway, such as CDH1 (E-cadherin), APC, and WIF1, are frequently silenced via dense methylation of their promoter regions in cervical cancer." (PMID 25826459, 2015). "Recent studies demonstrate that the WIF1 gene is down-regulated or silenced in astrocytomas, the most common tumors of the central nervous system, and in cervical cancer, both by aberrant promoter methylation." (PMID 24289328, 2013). "WIF1 was observed to have elevated methylation in cervical cancers, with 46% with a MI >15%." (PMID 25826459, 2015). "For example, overexpression of HOTAIR increases cellular radioresistivity through the modulation of WIF-1, HIF-1α, and p21 in pancreatic ductal adenocarcinoma cells, cervical cancer cell lines, and HeLa and C33A cells, respectively." (PMID 36457703, 2022). "Pyrosequencing analysis confirmed earlier studies indicating that DAPK1, SLIT2, WIF1 and RARB genes are common targets for aberrant methylation in cervical cancer." (PMID 25826459, 2015). "Herein, we identified an epigenetic biomarker panel (DAPK1, SLIT2, WIF1 and RARB) that distinguished cervical cancers from normal cytology samples." (PMID 25826459, 2015). "Specifically, WNT inhibitory factor 1, a secreted WNT antagonist, was found to be downregulated in human cervical cancer tissues, and to be able to inhibit cervical cancer cell proliferation and invasion in vitro and in vivo through inhibition of the WNT/β-catenin pathway." (PMID 32301035, 2020). "We confirmed that DAPK1, RARB, SLIT2, and WIF1 are aberrantly methylated in cervical cancer compared to normal tissue, whereas, APC, CDH1 and FHIT are less commonly methylated." (PMID 25826459, 2015). "Alterations in DNA methylation of specific genes in cervical cancers, such as DAPK1, RARB, WIF1, and SLIT2, may also occur early in cervical carcinogenesis and should be evaluated." (PMID 25826459, 2015). "Prominent alterations in DNA methylation in cervical cancers, such as shown for DAPK1, SLIT2, WIF1 and RARB, may also be early molecular events in cervical carcinogenesis and using the pyrosequencing assays developed here should be further tested in CIN3 lesions." (PMID 25826459, 2015).
prostate carcinoma (13 papers, 2009 to 2025). A carcinoma that arises from epithelial cells of the prostate gland. "Down-regulation of the Wnt/β-catenin signaling inhibitor WIF1, in this respect, is of interest because down regulation of WIF-1 in prostate cancer cells was observed to be associated with an increased capacity for cell migration and invasion." (PMID 22295114, 2012). "WIF1 has been found to increase sensitivity of prostate cancer patients to paclitaxel and etoposide." (PMID 39091989, 2024). "The latest clinical trial on this matter has been the use of Wnt inhibiting factor 1 (WIF1) in prostate cancer." (PMID 39091989, 2024). "Loss of expression of the genes WNT Inhibitory Factor 1 (WIF1) and Secreted Frizzled Related Protein 1 (sFRP1), due to promotor methylation inhibits Wnt signaling and is associated with prostate cancer." (PMID 35201496, 2021). "Restoration of WIF1 expression resulted in decreased motility and invasiveness of prostate cancer cells." (PMID 22325146, 2012). "Additionally, WIF1 has been found to enhance chemosensitivity of prostate cancer to certain anticancer drugs, including paclitaxel and etoposide, suggesting a potential role for WIF1 in improving treatment outcomes." (PMID 40430852, 2025). "However, WIF1 epigenetic changes such as promoter methylation have been identified in several human malignancies (including prostate cancer), resulting in WIF1 depletion and augmented Wnt signaling." (PMID 35204808, 2022). "Other studies have shown that Wnt inhibitory factor-1 (WIF1) is down-regulated in prostate cancer, and induced overexpression of WIF1 reverses EMT in prostate cancer cell lines and decreases their invasive capacity in vitro and in vivo." (PMID 24212796, 2011). "In addition, another negative regulator of Wnt that reduces tumor growth, cell migration and invasion, Wnt inhibitory factor 1 (WIF1), has also been suggested to be hypermethylated in prostate cancers." (PMID 22494660, 2012). "Also, when prostate cancer cell lines were transfected with WIF1, they were more sensitive to chemotherapy and had reduced phosphorylation of Akt (a key effector of PI3K signaling which is frequently phosphorylated in prostate cancer)." (PMID 24212796, 2011). "Moreover, several human prostate cancer cell lines (LNCaP, LAPC4, PC-3, DU-145, C4-2B, PC3-M, and LN4, but not 22Rv1) lack WIF1 mRNA expression owing to promoter hypermethylation." (PMID 35204808, 2022).
hepatocellular carcinoma (10 papers, 2010 to 2025). A malignant tumor that arises from hepatocytes. "Overall, the present study revealed that ANGPTL8 affects mRNA expression of two key regulators of Wnt signaling pathway, β-catenin and WIF-1, and inhibits proliferation of the hepatocellular carcinoma cell line HepG2 moderately." (PMID 31998458, 2019). "WIF1 expression was found to be frequently down-regulated in hepatocellular carcinoma; this down-regulation could be attributed to hypermethylation of the WIF1 promoter." (PMID 24289328, 2013). "Studies with mouse tumor models of hepatocellular carcinoma (HCC) have shown that administration of WNT inhibitors (WIF-1, sFRP1) reduces the density of tumor vasculature, endothelial progenitor migration, and expression of pro-angiogenesis factors." (PMID 29081735, 2017). "miR-181a promotes the development of hepatocellular carcinoma by regulating PTEN, CBX7, WIF1, and HOXB5." (PMID 36421826, 2022).
adenoma (9 papers, 2008 to 2023). A neoplasm arising from the epithelium. "Differential gene expression analysis of the scRNA-seq data from the adenoma cells showed substantially fewer transcripts encoding the Wnt antagonists Axin2, Dkk2, Dkk3, Wif1, Notum, and Nkd1 in the LApcL mice than in the LApc mice." (PMID 34788095, 2021). "Of the APC mutated adenomas 83% (33/40) showed WIF-1 methylation and of the APC wild type adenomas 61% (25/41) showed WIF-1 methylation (p = 0.048)." (PMID 24350795, 2013). "Closer analysis of these adenomas reveals a significant increase in Notum and elevated Wif1 expression in response to long-term caffeine treatment, whereas Dkk2 expression is unaltered." (PMID 37364735, 2023). "Nevertheless there is an earlier study on plasma methylation of RASSF2A, APC, MGMT and Wif-1 that suggested a more promising biomarker panel for adenoma with sensitivity of 86.5% and specificity of 92.1%." (PMID 29765549, 2018). "In the current study we observed more frequent WIF-1 methylation in left-sided adenomas compared to right-sided adenomas." (PMID 24350795, 2013). "Combining both adenoma types, a positive trend between APC mutation and both WIF-1 and DKK3 methylation was observed (p < 0.05)." (PMID 24350795, 2013). "Lower levels of methylation in carcinomas compared to adenomas have been described before for WIF-1 but also for other genes, such as p14 and ESR1." (PMID 24350795, 2013). "This led the authors to propose a role for WIF1 in facilitating adenoma growth, perhaps by inhibiting the generation and/or maintenance of the normal epithelial stem cell compartment." (PMID 18542073, 2008). "Furthermore, NotumKO adenomas display increased Wif1 expression, whereas Dkk3 expression remains unchanged." (PMID 37364735, 2023). "However, another study found that the WIF1 expression was unique to adenomas." (PMID 18542073, 2008). "To investigate the relation between methylation of SFRP2, WIF-1, DKK3 and SOX17 and the anatomical location of the adenoma, we divided all the adenomas into left- and right-sided adenomas." (PMID 24350795, 2013). "Methylation of SFRP2, WIF-1, DKK3 and SOX17 was significantly higher in carcinomas as well as both types of adenomas compared to normal colorectal mucosa." (PMID 24350795, 2013). "Although methylated markers such as RASSF1A, SDC2, BCAT1, IKZF1, ALX4, SDC2 and WIF-1, among others, have demonstrated some usefulness for the detection of established cancers, the goal of detecting precancerous adenomas has not been achieved yet." (PMID 32605302, 2020). "We discovered widespread hypermethylation of the Wnt antagonists SFRP1, SFRP2, SFRP5, DKK2, WIF1 and SOX17 in the transition from normal to adenoma with only the Wnt antagonists SFRP1, SFRP2, DKK2 and WIF1 showing further significant increase in methylation from adenoma to carcinoma." (PMID 25432628, 2014). "Interestingly, we found lower WIF-1 methylation frequencies in carcinomas compared to polypoid adenomas (WIF-1; 47% versus 87%) but not compared to nonpolypoid adenomas." (PMID 24350795, 2013). "The present study focussed on promoter methylation of four known Wnt-pathway antagonists (SFRP2, WIF-1, DKK3 and SOX17), in polypoid and nonpolypoid adenomas, and its possible association with other molecular events that can play a role in Wnt-pathway activation." (PMID 24350795, 2013). "WIF-1 and DKK3 showed a significantly lower level of methylation in nonpolypoid compared to polypoid adenomas (p < 0.01)." (PMID 24350795, 2013). "For APC methylation as well as for chromosome 5q loss, no relation was found with the promoter methylation results for SFRP2, WIF-1, DKK3 and SOX17 when combining both adenomas types or in nonpolypoid adenomas or polypoid adenomas, separately." (PMID 24350795, 2013). "We found higher levels of methylation for WIF-1 and DKK3 in polypoid adenomas compared to nonpolypoid adenomas." (PMID 24350795, 2013).
adenoma (continued). "Interestingly, DKK3 and WIF-1 methylation frequencies were significantly higher in polypoid adenomas (DKK3; 97% (38/39), WIF-1; 87% (34/39)) compared to nonpolypoid adenomas (DKK3; 76% (32/42), WIF-1; 57% (24/42); p = 0.005 and p = 0.003, respectively)." (PMID 24350795, 2013).
non-small cell lung carcinoma (8 papers, 2014 to 2019). A group of at least three distinct histological types of lung cancer, including non-small cell squamous cell carcinoma, adenocarcinoma, and large cell carcinoma. "It was shown that WIF1 had the potential as a methylation biomarker in the diagnosis of non small cell lung cancer (NSCLC)." (PMID 31195961, 2019). "In human non-small cell lung cancer, norcantharidin treatment was found to inhibit tumor cell proliferation and invasion by promoting WIF1 demethylation." (PMID 28484252, 2017). "The relationship between WIF-1, Gsk-3β and nm23-H1 expression and the prognosis in patient with non-small cell lung cancer." (PMID 27911280, 2017). "Negative regulation of canonical Wnt signalling by miR-29 has been shown to be via targeting of DNMT3A and 3B to demethylate WIF-1 in non-small-cell lung cancer." (PMID 26687115, 2016). "In conclusion, we identified significant associations between seven genes (CDKN2A, RASSF1, MGMT, RARB, DAPK, WIF1 and FHIT) and smoking behavior in non-small cell lung cancer patients." (PMID 25754026, 2015).
pancreatic ductal adenocarcinoma (8 papers, 2017 to 2025). An infiltrating adenocarcinoma that arises from the epithelial cells of the pancreas. "Further, the overexpression of ALKBH5 significantly inhibited the proliferation, migration, and invasion of pancreatic ductal adenocarcinoma (PDAC) cells by inhibiting the transactivation of Wnt inhibitory factor 1 (WIF-1)." (PMID 40136363, 2025). "Overexpression of WIF-1 inhibits the Wnt signaling pathway, increasing the sensitivity of pancreatic ductal adenocarcinoma cells to gemcitabine." (PMID 33926508, 2021). "In pancreatic ductal adenocarcinoma, ALKBH5 can reduce the m6A modification on WIF1 mRNA and enhance its stability." (PMID 33926508, 2021). "HOTAIR expression was markedly increased in the pancreatic ductal adenocarcinoma (PDAC) cell lines and tissues, and HOTAIR silencing improved the radiosensitivity of PDAC cells via regulating the expression of Wnt inhibitory factor 1 (WIF-1)." (PMID 28376901, 2017).
breast tumors (6 papers, 2010 to 2022). "With regard to activation of the canonical Wnt pathway, we observed that RSPO3‐driven breast tumors expressed the Wnt/β‐catenin target genes Axin2, Wif1, Znrf3, and Ctnnb1 itself, however at significantly lower levels than their WNT1‐driven counterparts." (PMID 36106661, 2022). "Elevated expression of DNA methyltransferases (DNMTs), mainly DNMT1 and DNMT3B, has been reported to be largely responsible for the aberrant WIF1 hypermethylation in breast tumors." (PMID 25918249, 2015). "In addition to this, epigenetic silencing of the Wnt antagonists secreted Frizzled-related proteins (sFRPs) and Wnt inhibitory factor-1 (WIF-1) leads to aberrant regulation of Wnt/β-catenin signaling in both primary breast tumours and cell lines." (PMID 25499975, 2014). "The majority of breast tumors exhibit evidence of activation of canonical Wnt/β-catenin signaling and alterations predicted to upregulate Wnt/β-catenin signaling have been reported, including epigenetic silencing of Wnt antagonists SFRP1 and WIF1 and upregulation of Wnt ligands and Fzd receptors." (PMID 20126544, 2010).